SETD2 (SET domain containing 2, histone lysine methyltransferase)
Diseases named in the same sentence as SETD2 in open-access papers (continued):
Sharing a sentence is not in itself a finding about the gene and the disease.
cancer (continued). "Inactivating mutations in PBRM1, SETD2, KDM5C and BAP1 tend to be focal in the tumors, so therapies that are designed to exploit the weakness induced by mutation of an individual gene could be problematic since it cannot treat the remaining cancer cells free of that mutation." (PMID 30355451, 2018). "Strikingly, both sample sets shared six genes in their ‘top 20’ list of most frequently lost ‘Cancer census genes’ (i.e. EP300, SETD2, PBRM1, CHEK2, MKL1 and MAPK1)." (PMID 29371938, 2017). "Six other ‘Cancer census genes’ however, were listed among the most frequently lost ones, both in the TCGA- and LP-WGS-dataset (i.e. EP300, SETD2, PBRM1, CHEK2, MKL1 and MAPK1)." (PMID 29371938, 2017). "SETD2 and BAP1 both lie on the short arm of chromosome 3, undergo copy-neutral LOH or deletion and are driver genes for ccRCC and other cancer types." (PMID 25790038, 2015). "Studying EMT in cancer cell lines that express known oncogenes (e.g., PTEN, KRAS) may confound the contribution of SETD2 to the process of tumorigenesis." (PMID 37418588, 2024). "This study aimed to determine whether SETD2 dysfunction is a complementary or independent factor of MSH-H and TMB, and whether this type of dysfunction acts differently in various types of cancer." (PMID 37479966, 2023). "Additionally, sufficient studies have suggested that SETD2, BAP1, mTOR, MUC16, HMCN1, KDM5C, ARID1A, and PTEN are intimately tied to prognosis and immune response in cancers." (PMID 35936012, 2022). "Cancer types that displayed the largest differences between groups were LGG (IDH1 1% in the low- versus 95% in the high-methylation group), GBM (IDH1 0% versus 88%), LAML (IDH1 6% versus 56%; IDH2 3% versus 44%) and KIRC (SETD2 0% versus 36%)." (PMID 35134107, 2022). "Considering their crucial role in the epigenetic regulation of cancer processes, selective inhibition of the histone methyltransferases NSD1, SETD2 and EZH2 could offer beneficial therapeutic strategies in treating cancer." (PMID 36230787, 2022). "To further validate the association between SETD2 mutation and MSI status, we also examined the MSI MANTIS10 scores in patients with SETD2 mutant cancer (0.32, 0.30–0.34) and patients with SETD2 nonmutant cancer (0.31, 0.29–0.33; P < 0.0001)." (PMID 34127768, 2021). "The prognosis and survival for cancer patients in TCGA cohort were independent of SETD2 mutant status." (PMID 34127768, 2021). "Given the relevance of SETD2 in cancer, we set out to identify new non-nucleoside SETD2 inhibitor compounds by virtual screening." (PMID 34576219, 2021). "First, SETD2 was found to catalyze the methylation of H3K36 and have an anti-cancer effect." (PMID 32859239, 2020). "To validate our hypothesis, we decided to examine the ISGF3 protein levels in ccRCC cancer cells with IHC and correlate their protein levels with the protein levels of BAP1, PBRM1, and SETD2." (PMID 30355451, 2018). "The Cancer Genome Atlas Research Network supports the fundamental role of oxygen-sensing genes (VHL) and chromatin remodeling genes (PBRM1, BAP1 and SETD2) in RCC tumorigenesis, highlighting their potential as prognostic biomarkers and/or future therapeutic targets." (PMID 26452128, 2015).
cancer (continued). "To date, there have not been reports on the targeted therapy for SETD2 in any cancer type, let alone RCC." (PMID 25853938, 2015). "Moreover, beyond the role of this enzyme in epigenetics and H3K36me3-dependent processes, we highlight the putative role of "non-epigenetic/H3K36me3" functions of SETD2 in cancer, particularly those involving the cytoskeleton." (PMID 39591760, 2025). "A recent multi-gene 3p analysis conducted in a preclinical study on cell line and cell culture in mice suggests a possible negative predictive effect of SETD2 alterations for ICI-based regimens, whereas pan-cancer work links SETD2 mutation to a more “inflamed” phenotype." (PMID 41440218, 2025). "SETD2 is absent or reduced in several cancers, supporting a tumor suppressive role of the protein." (PMID 37372360, 2023). "In other non-neuronal models of cancer, NfKB has been linked to inhibition of nuclear receptor binding SET domain protein 1 (NSD1) and SET domain containing 2 (SetD2), two H3K36 histone methyltransferases, which are linked to longevity, though not general to chromatin silencing." (PMID 30983962, 2019). "Since our hypothesis is that BAP1, PBRM1, KDM5C, SETD2 are critical to maintain the expression and/or function of ISGF3 subunits in the ccRCC cancer cells, we concluded that mRNA levels in the bulk tumors from the TCGA dataset are not suitable for our validation experiments." (PMID 30355451, 2018). "Thus, SETD2 appears to be crucial for a proper embryonic development although many cancer cells appear to function well without SETD2." (PMID 27191891, 2016). "To investigate whether SETD2 exacerbates SMAD4‐dificiency CRC, we first consulted the clinical data samples of CRC in the TCGA database and analysed the expression levels of SETD2 and SMAD4 in the samples of CRC patients and their relationship with cancer stage and survival rate." (PMID 37962020, 2023). "Given the preclinical evidence, whether SETD2 dysfunction was a complementary or independent factor to MSH-H and TMB to predict the prognostic of ICIs treatment needed to be figure out and whether this kind of dysfunction acted differently in different cancer types warrants further study." (PMID 37479966, 2023). "Co-occurring of genetic mutations in cancers with KDM5C alterations were not uncommon in both early-stage and advanced stage cohort and some of them are prevalent driver genes (e.g., LRP2, KMT2C, PBRM1, NOTCH1, FAT1, SETD2, NSD1, etc.), while their clinical significance remained undetermined." (PMID 33953726, 2021). "However, two factors have been identified in cancer-related studies that can modulate the level of SETD2 in cancer cells, and may also do so in non-cancerous cells." (PMID 27191891, 2016). "Since inactivation of both EZH2 and SETD2 leads to aberrant methylation at the respective histone H3 lysine residue, it is unclear why H3K27M and H3K36M are not as frequent as expected in these cancers." (PMID 30101054, 2018).
neurodevelopmental disorder (6 papers, 2021 to 2026). A behavioral and cognitive disorder with onset during the developmental period that involves impaired or aberrant development of intellectual, motor, or social functions. "Recently, de novo SETD2 variants have been reported in neurodevelopmental disorders including autism spectrum disorder (ASD)." (PMID 40469903, 2025). "SETD5 and SETD2 genes share functional similarities such as playing multiple roles in the central nervous system through histone and nonhistone methylation, and their dysfunction leads to complex neurodevelopmental disorders." (PMID 40642607, 2025). "For example, mutations in the SETD2 gene, which encodes a methyltransferase responsible for H3K36me3, have been associated with ASD (case report) and neurodevelopmental disorders with or without macrocephaly overgrowth, highlighting the importance of this modification in brain development." (PMID 40469903, 2025).
hematologic malignancies (5 papers, 2020 to 2026). "SETD2 mutations play an important role in the development and treatment of hematologic malignancies." (PMID 37359376, 2023). "SETD2 loss of function has been observed in solid and hematologic malignancies." (PMID 36894973, 2023).
infection (4 papers, 2021 to 2025). The state of being infected such as from the introduction of a foreign agent such as serum, vaccine, antigenic substance or organism. "Variation in SETD2 expression or activity and/or abundance of H3K36me3 could impact whether a given infected cell adopts a latent or active infection phenotype." (PMID 38848441, 2024).
neurodegenerative disease (4 papers, 2022 to 2025). A disorder of the central nervous system characterized by gradual and progressive loss of neural tissue and neurologic function. "Beyond its role in DNA repair, SETD2 profoundly impacts the nervous system, particularly in the context of neurodegenerative diseases." (PMID 40469903, 2025). "Regarding neurodegenerative diseases, SETD2 has been shown to be involved in the mechanism promoting HD." (PMID 39765675, 2024). "In summary, SETD2’s interaction with the HTT in the nervous system exemplifies its critical role in neurodegenerative disease pathology." (PMID 40469903, 2025).
immune disorders (2 papers, 2021 to 2025). "We will also summarize the implication of SETD2 dysregulation in immune disorders and the progress of several epigenetic drugs that target SETD2." (PMID 40746737, 2025).
neoplasms of the central nervous system (2 papers, 2018 to 2019). "A total of 22 CNS tumors with SETD2 mutations were identified across the cohorts included in the TCGA datasets, with 0–14% of CNS tumors harboring a SETD2 mutation depending on the cohort." (PMID 30419952, 2018). "If SETD2 mutations are indeed driving tumorigenesis in some CNS tumors, the exact mechanism by which this occurs also requires further elucidation." (PMID 30419952, 2018). "We investigated SETD2 mutations in a cohort of approximately 640 CNS tumors via next generation sequencing; 23 mutations were detected across 19 primary CNS tumors." (PMID 30419952, 2018). "For example, the most significant decreases in staining for H3K36me3 in non-CNS tumors with SETD2 mutations were seen when both SETD2 allelic copies were lost." (PMID 30419952, 2018). "Mutations in SETD2 are found in many tumors, including neoplasms of the central nervous system." (PMID 30871634, 2019). "SETD2 mutations have also been reported in neoplasms of the central nervous system (CNS)." (PMID 30419952, 2018). "Data on the long-term survival for patients with SETD2-mutant CNS tumors is limited." (PMID 30419952, 2018).
metabolic disorder (1 paper, 2023). "Here, we found that a paternal high-fat diet significantly altered the methylation levels and expression of the SETD2 promoter region in sperm, which may be related to the metabolic disorder in the testes induced by a high-fat diet." (PMID 37598138, 2023).
neurological disorder (1 paper, 2023). "Our findings expand the genotype-phenotype knowledge of SETD2-associated neurological disorder and provide new evidence for further genetic counselling." (PMID 37025455, 2023).
renal diseases (1 paper, 2023). "Few studies have been conducted between SETD2 and the TGF‐β/Smad signalling pathway, especially in the field of renal diseases." (PMID 37933774, 2023).
SETD2 also shares sentences with these, for which no sentence is quoted: diffuse large B-cell lymphoma (6 papers); adenocarcinoma (3); urothelial carcinoma (3); uterine corpus endometrial carcinoma (3); angiosarcoma (2); astrocytoma (2); brain disorder (2); colon adenocarcinoma (2); colorectal adenocarcinoma (2); high grade glioma (2); lung squamous cell carcinoma (2); meningioma (2); myeloproliferative disorder (2); peritoneal mesothelioma (2); acute monocytic leukemia (1); acute promyelocytic leukemia (1); aggressive (1); albinism (1); anaplastic astrocytoma (1); anemia (1); aneurysmal bone cyst (1); atherosclerosis (1); bacteremia (1); bladder tumours (1); bladder urothelial carcinoma (1); celiac disease (1); cholangiocarcinoma (1); chondroblastic osteosarcoma (1); choroid plexus papilloma (1); ciliary dyskinesia (1).
A further 71 diseases each share a sentence with SETD2 in 1 paper.